IL6R (interleukin 6 receptor)
Diseases named in the same sentence as IL6R in open-access papers (continued):
Sharing a sentence is not in itself a finding about the gene and the disease.
COVID-19 (continued). "A retrospective observational study showed that treatment with the biological agent Tocilizumab, which targets IL-6R, was effective in 46.7% of critically ill COVID-19 patients." (PMID 38165854, 2024). "In this study, bioinformatics integration showed that the IL-6R gene expression level was significantly higher in COVID-19 peripheral blood monocytes than in the healthy controls." (PMID 38165854, 2024). "GSE164805 and GSE171110 dataset validation revealed significant differences between the COVID-19 and normal controls in four core genes (feature genes), namely IL6R, TLR4, TLR2, and IFNG." (PMID 38165854, 2024). "Despite transforming the treatment options for COVID-19, IL-6R inhibition is still ineffective in a fraction of patients." (PMID 37215114, 2023). "Recently, the interleukin-6 receptor inhibitor tocilizumab demonstrated improved clinical outcome in severe COVID-19 patients." (PMID 37587219, 2023). "The premise of our study was that interleukin-6 receptor blocking, when administered to patients with sickness that had not yet resulted in intubation, would stop the cytokine storm brought on by COVID-19 and avert the worst effects of the disease." (PMID 36833140, 2023). "Among these compounds, the IL-6 receptor (IL-6R) inhibitor tocilizumab (TCZ) has been effective in several randomized clinical trials (RCT) in Stage 2b-3 COVID-19." (PMID 36830885, 2023). "We also confirm the previously reported protective effect of IL6R blockade on severe COVID-19 (OR = 0.69, 95% CI 0.57 to 0.84) in the COVID-19 HGI, which was of similar magnitude to that seen in sepsis." (PMID 36716318, 2023). "Another potential COVID-19 therapeutic target, tocilizumab, has the ability to bind IL-6R, therefore blocking the downstream effects of IL6 over-induction." (PMID 37043472, 2023). "Tocilizumab, a monoclonal antibody against IL-6R used to treat multiple inflammatory diseases, improved outcomes in patients with severe COVID-19." (PMID 36941580, 2023). "In this context, polymorphisms at IL6, IL6R, and IL6ST genes become interesting candidates to be prognostic and predictive markers of COVID-19 severity." (PMID 37243282, 2023). "In a number of ongoing COVID-19 clinical trials, IL-6/IL-6R inhibitors were employed preliminarily, and further inter-clinical trials are presently underway." (PMID 37124230, 2023). "IL-6, an important player in COVID-19, binds IL-6R and gp130 receptors to activate JAK/STAT-3 pathway and then contributes to the CRS observed in COVID-19 and possibly in Long COVID patients." (PMID 36947108, 2023). "Tocilizumab (TCZ) is a humanized monoclonal antibody against the interleukin-6 receptor (IL-6R), applied in severe COVID-19 with hyperinflammation since early 2020." (PMID 36983429, 2023). "A recent study showed that the treatment of severe COVID-19 patients with sarilumab, a monoclonal antibody against IL-6R, promoted the recovery of cases with mild lung disease." (PMID 36793739, 2023). "The potential iatrogenic immunosuppression induced by Tocilizumab (antagonist of the interleukin-6 receptor), hydroxychloroquine or corticosteroids, after therapeutical used for severe COVID-19, was notified in a third of cases (4/11)." (PMID 36984617, 2023). "Notwithstanding uncertainty around the point estimates, MR estimates for IL6R blockade were larger in sepsis than in COVID-19, for the comparable disease severity." (PMID 36716318, 2023). "The authors have demonstrated an antitumor effect achieved in glioma; however, the similarity in IL-6R coupling mechanisms has the potential to be extended to COVID-19 induced inflammation." (PMID 36839968, 2023). "In 2021, a study demonstrated that if using tocilizumab, the anti-interleukin-6 receptor monoclonal antibody, the outcomes of patients with severe COVID-19 improved." (PMID 37367625, 2023).
COVID-19 (continued). "The clinical efficacy of anti-IL-6R in COVID-19 patients has been tested in a recent randomized, double-blind phase III COVACTA trial (NCT04320615; clinicaltrials.gov) but showed an insignificant decrease in fatality." (PMID 36992350, 2023). "For example, the interleukin-6 receptor antagonist tocilizumab has been approved for treatment of severe COVID-19." (PMID 36166068, 2023). "While IL6R is is already a therapeutic target for COVID-19, and SRRM1 has been reported in a previous pre-print, these were found in smaller cohorts and will require replication." (PMID 36327219, 2022). "The FDA has also approved the immune modulators for certain hospitalized adults with COVID-19, e.g., Olumiant (baricitinib), Interleukin-6 receptor blocker." (PMID 36015163, 2022). "Eight of ten COVID-19 patients in our study were treated with tocilizumab, an anti-IL-6 receptor (IL-6R) antibody." (PMID 35064122, 2022). "Tocilizumab is an anti-human interleukin 6 receptor monoclonal antibody that has been used to treat coronavirus disease 2019 (COVID-19)." (PMID 36102463, 2022). "We report, here, on two patients with COVID-19 and lymphoproliferative disorders treated with Tocilizumab (a humanized monoclonal antibody against the interleukin-6 receptor) and followed by an [18F]FDG PET/CT to early evaluate the therapy’s efficacy." (PMID 36579547, 2022). "Here, we assess the relationship between IL-6 signalling variables [IL-6, soluble IL-6R (sIL-6R) and soluble gp130 (sgp130)] and outcomes in a cohort of 366 COVID-19 patients." (PMID 35634332, 2022). "Although the heterogenous pathologies likely have different mechanisms and therapeutic targets, it is promising that at least the pulmonary manifestations of COVID-19 are amenable to immunosuppressant treatment, such as dexamethasone and anti-IL-6R." (PMID 35665037, 2022). "Tocilizumab is a monoclonal antibody against interleukin-6 receptor that can reduce macrophage activation syndrome-induced cytokine storm and is beneficial in some series of COVID-19 cases." (PMID 36340438, 2022). "A plasma immunoglobulin (Gammaraas®) and/or tocilizumab (interleukin-6 receptor antagonist; Actemra®) injection was utilised to treat the cytokine storm while remdesivir and oseltamivir were administered to ameliorate COVID-19." (PMID 35077495, 2022). "The numbers of patients and events were too low to allow definitive conclusions to be drawn, but this study contributes valuable information about the role of subcutaneous IL-6R inhibition in the treatment of hospitalized COVID-19 patients." (PMID 35213547, 2022). "In controlled clinical trials throughout the world, IL-6 and IL-6R antagonists are being evaluated for the treatment of COVID-19 patients with severe respiratory difficulties." (PMID 36506506, 2022). "New reliability and output data on IL-6 and IL-6R targeting will emerge to implement more individualized therapies that work better to control the systemic impact of COVID-19." (PMID 35457086, 2022). "We analysed inhibition of C-reactive protein (CRP) – a biomarker for IL-6 activity – in patients with COVID-19 or idiopathic multicentric Castleman disease (iMCD) treated with tocilizumab (anti-IL-6R) or siltuximab (anti-IL-6), respectively." (PMID 35928820, 2022). "An important evolution in the management of severe COVID-19 was the use of corticosteroids and interleukin-6 receptor (IL-6R) antagonists." (PMID 35606884, 2022). "The downregulation of these miRNAs in patients with COVID-19 leads to IL-6/IL-6R hyperactivation by directly targeting the 3'UTR of IL-6/IL-6R, thereby enhancing the cytokine storm induced by SARS-CoV-2 infection." (PMID 35928726, 2022). "IL-6 inhibitors are widely available for use in the treatment of COVID-19 as monoclonal antibodies targeting IL-6 (siltuximab) or IL-6R (tocilizumab and sarilumab)." (PMID 36115998, 2022).
COVID-19 (continued). "As an example, genetically-predicted IL6R showed a marginally protective effect on COVID-19 severity in European ancestry (OR=0.890, 95%CI=0.827 to 0.970, P = 2.84 × 10−3)." (PMID 35772218, 2022). "NK cell hyperactivation, likely driven by IL-6, IL6R and IL-18 is a feature of severe COVID-19 as compared to mild or moderate disease." (PMID 36160152, 2022). "Our model shows that, in a situation with rapid, high, dysregulated IL-6 production – such as severe COVID-19 or a cytokine storm – an initial dose of either an anti-IL-6 or anti-IL-6R mAb inhibits IL-6 bioactivity." (PMID 35928820, 2022). "A recent study reported that administration of an interleukin-6 receptor antagonist (tocilizumab) to patients with severe COVID-19 provided a therapeutic benefit, and more patients are being enrolled in clinical trials testing the efficacy of this agent." (PMID 34088317, 2021). "Interleukin-6 receptor antagonists (IL-6RAs) and steroids are emerging immunomodulatory therapies for severe and critical coronavirus disease (COVID-19)." (PMID 34600589, 2021). "Tocilizumab is a humanized monoclonal antibody against the interleukin-6 receptor, which has been reported to be one of the most important cytokines involved in COVID-19." (PMID 33635275, 2021). "In this study, we highlight the potential for a plant-made anti-IL-6R mAb to be used as a therapeutic, with specific emphasis to the cytokine release syndrome observed in some critically ill COVID-19 patients." (PMID 34835296, 2021). "Within this context, the antagonistic blockade of IL-6R implemented by tocilizumab appears as a very interesting approach for treatment of severe COVID-19 patients." (PMID 33802761, 2021). "Tocilizumab (Hoffmann-LaRoche) is a humanized IgG1 also targeting IL-6R, marketed for several indications and is currently tested in 42 clinical trials in COVID-19 patients." (PMID 33668613, 2021). "Additional lineage-specific DC alterations in severe COVID-19 included down-regulation of IL-6R in DC1 and a drastic decrease of the inhibitory receptor CD200R in the cDC2 lineage, including circulating progenitors." (PMID 33479167, 2021). "The results showed that IL6R/IL6/IL6ST (PDB ID: 1P9M) had high level of CDOCKER interaction energy with the Spike protein of COVID-19 (PDB ID: 6VXX)." (PMID 34731090, 2021). "Tocilizumab, a humanized monoclonal antibody directly targeting the IL-6R, significantly improves lung function in COVID-19 and was also reported to be efficient in case reports of sarcoidosis-associated posterior uveitis." (PMID 34440765, 2021). "In the treatment of critical COVID-19 patients, the anti-IL-6 receptor (IL-6R) antibody tocilizumab, which can bind to both membrane-bound and soluble IL-6R, blocked downstream signal transduction and improved the prognosis." (PMID 34335278, 2021). "IL-6 is one of the key pro-inflammatory cytokines found in COVID-19 patients, which is why anti-IL-6/IL-6R biological drugs have been used for the treatment of this disease from the beginning." (PMID 34073559, 2021). "Tocilizumab is a humanized monoclonal antibody against both the soluble and membrane-bound interleukin-6 receptor and therefore useful when IL6 is high as part of the COVID-19-associated cytokine storm." (PMID 34364393, 2021). "Tocilizumab is a humanized monoclonal antibody against the interleukin-6 receptor that works by damping the cytokine release syndrome observed in COVID-19 patients." (PMID 34777868, 2021). "During the severe stage of COVID-19, the inhibition of the IL-6 receptor (IL-6R) is being tested in clinical trials, and it has shown promising results in decreasing the cytokine release syndrome in COVID-19 patients." (PMID 33613573, 2021). "Searching for monoclonal antibodies of IL-6 or IL-6R will be critical for development of COVID-19 therapeutic drugs." (PMID 37287491, 2021).
COVID-19 (continued). "Unsurprisingly, anti-cytokine agents including anti-IL-1R and anti-IL6R antagonists were among important candidates in the therapy of later stages of COVID-19." (PMID 33918563, 2021). "On the one hand, IL-6 binds to membrane IL-6 receptor (IL-6R) and induces the production of acute-phase proteins such as CRP and fibrinogen, biomarkers associated with poor COVID-19 outcomes." (PMID 34276355, 2021). "Tocilizumab is a recombinant, anti-human IL-6R monoclonal antibody that inhibits hyperinflammation in patients with COVID-19." (PMID 33959261, 2021). "Overall, the available clinical evidence suggests a benefit of IL-6R antagonists as therapeutics in patients with COVID-19." (PMID 34253862, 2021). "A small clinical trial with 20 COVID-19 patients proved the clinical efficacy of anti-IL-6R antibodies in severe cases of COVID-19." (PMID 32668803, 2020). "At present, blockers of IL-6/IL-6R have been preliminarily applied in a series of ongoing clinical trials of COVID-19 and further multi-center clinical trials are being carried out." (PMID 33329533, 2020). "It is an IL-6 receptor (IL-6R) blocker that can effectively block the IL-6 signal transduction pathway and thus is likely to become an effective drug for patients with severe COVID-19 and to reduce the mortality." (PMID 32806657, 2020). "The findings directly provide the evidence supporting the favorable outcomes of IL-6R blockers tocilizumab treatment in COVID-19 patients." (PMID 32727465, 2020). "As the ∼1600 COVID-19 patients received IL-6/IL-6R blocking mAbs at the severe and critical stages, it is reasonable to expect that early treatment at stage 1 would have better outcomes." (PMID 32766256, 2020). "Neutralizing IL-6 or its receptor by using anti-IL-6 or anti-IL-6R antibodies, respectively, is being currently investigated to help severe cases of COVID-19 that suffer from complications derived from cytokine storm." (PMID 33324210, 2020). "Consistent with this notion, several small clinical studies using IL-6R inhibitors to treat COVID-19 patients at different stages showed opposite outcomes." (PMID 32766256, 2020). "This systematic review and meta-analysis aimed to assess the safety and efficacy of anti-IL-6 signaling (anti-IL6/IL-6R/JAK) agents on COVID-19 based on the current evidence." (PMID 33384605, 2020). "In this meta-analysis and systemic review, we pooled data from all available studies with acceptable quality to assess the effects of anti-IL-6/IL-6R/JAK antibodies on COVID-19." (PMID 33384605, 2020). "When present at abnormally high levels, IL-6 in conjunction with soluble IL-6R compromises endothelial cells and the vasculature in experimental conditions (Section 4.3), and IL-6 peak levels mark disease severity in COVID-19." (PMID 32629875, 2020). "Systemic inflammation in COVID-19 patients is a participant effector that magnifies vascular pathology, as it includes the pro-coagulant mediators IL-6 plus IL-6R, which induce the vascular-permeability effector VEGFA." (PMID 32629875, 2020). "The strong positive correlation between circulating IL-6 levels and illness severity in hospitalized COVID-19 patients provides the rationale for deployment of IL-6R inhibitors in a selection of infected patients." (PMID 33584679, 2020). "Many reports have presented the clinical efficacy of IL-6 blockade in treating ∼1600 severe/critically ill COVID-19 patients using the anti-IL-6R monoclonal antibodies tocilizumab, or sarilumab, and IL-6 neutralizing antibody siltuximab." (PMID 32766256, 2020). "As per the observed link between autoimmunity and COVID-19, drugs commonly used in AD, such as corticosteroids, and IL-6R and IL-1 antagonists, are being tested and used in COVID-19 cases." (PMID 33414783, 2020). "Very recently, administration of the anti-IL-6-Rα antibody tocilizumab has been proposed as a treatment in clinical practice by ameliorating inflammation of COVID-19 patients." (PMID 32228226, 2020).
COVID-19 (continued). "Tocilizumab (Actemra, Roche) is a humanized monoclonal antibody against the interleukin-6 receptor (IL-6R) approved for the treatment of seriously ill COVID-19 patients with elevated IL-6 by the National Health Commission of China." (PMID 33041830, 2020). "In this study, we retrospectively observed tocilizumab, an IL6R inhibitor, in treatment of 21 patients with severe and critical COVID-19." (PMID 32350134, 2020). "Furthermore, the Immunomodulators used for the treatment of COVID-19 are antibodies that usually target IL-6, IL-6R, and other interleukins that are also components of the cytokine storm." (PMID 40149530, 2025). "The results revealed that polymorphisms in the IL6, IL6R, IL1α, IL1R, IFNγ, TNFα, CRP, VDR, VDBP, and ACE2 genes are the most significant genetic factors influencing COVID-19 prognosis, particularly in terms of the risks of COVID-19 pneumonia, mortality, rehospitalization, and associated mortality." (PMID 40869297, 2025). "The use of immunomodulatory drugs in patients with COVID-19, such as corticosteroids and the interleukin-6 receptor (IL-6R) blocker tocilizumab, may also result in an increased risk of IPA." (PMID 40863508, 2025). "Similar to IL6R, we found genetic IL6 downregulation to be associated with lower risk of hospital admission due to sepsis and a sepsis diagnosis in individuals <75 years, as well as hospitalization due to COVID-19." (PMID 40858837, 2025). "Although anecdotal data on IL6 inhibitors (e.g. anti-IL6R antibody Tocilizumab) in pregnant women with inflammatory disorders such as rheumatoid arthritis or severe COVID-19 during pregnancy are reported, systematic studies of safety and efficacy have not been reported thus far." (PMID 38895127, 2024). "Despite these limitations, our study has some obvious strengths, especially using the hypothesis-driven approach, we provide insight into the specific roles of IL6 and IL6R in COVID-19 progression, providing targeted insights into this crucial pathway." (PMID 39040605, 2024). "In conclusion, this study revealed that IL-6R, TLR4, TLR2, and IFNG may be potential pathogenic genes in the CRS associated with COVID-19." (PMID 38165854, 2024). "IL6R, TLR4, TLR2, and IFNG may be potential pathogenic genes and therapeutic targets for the CRS associated with COVID-19." (PMID 38165854, 2024). "Moreover, differential gene expression analysis revealed that IL6R expression was significantly increased in total monocytes and reduced in neutrophils of COVID-19 patients." (PMID 39835136, 2024). "Tocilizumab, a monoclonal antibody against the interleukin 6 receptor, may counteract the inflammatory cytokine release syndrome in patients with severe COVID-19 illness." (PMID 37179397, 2023). "To test this, we undertook a two-sample MR study to assess the potential impact of IL6R blockade on sepsis, COVID-19, as well as risk of infection in the absence of sepsis." (PMID 36716318, 2023). "Thus, our study suggests IL6/IL6R signaling as a plausible ‘downstream’ therapeutic target in IFNB1-overexpressing patients with COVID-19, which should be investigated in future clinical trials." (PMID 37217661, 2023). "Similarly, anti-IL-6 and anti-IL-6R antibodies, such as Sarilumab, Siltuximab and Tocilizumab have been tested for their ability to control virus-induced hyper-inflammation in COVID-19 patients." (PMID 37854602, 2023). "The ongoing ASSAIL-MI trial has shown the potential for anti-IL-6 treatment to increase myocardial salvage in STEMI patients at the time of reperfusion, whilst previous evidence has highlighted the anti-arrhythmic potential of anti-IL-6R therapy in patients with rheumatoid arthritis and COVID-19." (PMID 37668685, 2023). "Hence, the present study aims to evaluate the role of polymorphisms at IL6, IL6R, and IL6ST in COVID-19 severity aspects, along with their influence on IL-6 plasma levels during active COVID-19." (PMID 37243282, 2023).